TTC1 (tetratricopeptide repeat domain 1)
Description:
Adapter protein that plays a role downstream of GNA15 to stimulate Ras activation and subsequent phosphorylation of ERK1/2 independently of phospholipase Cbeta signaling. Mechanistically, interacts with GNA15 and SOS2 to form a macromolecular signaling complex which has a high affinity for HRAS. Additionally, participates in signaling via other G-alpha proteins like GNA14, activating NF-kappa-B through Ras and ERK pathways. Beyond signaling, supports protein homeostasis by cooperating with HSP40 in the HSP70 chaperone cycle, promoting protein folding through the regulated dissociation of the HSP70 inhibitor HSPBP1.
Synonyms: TPR1
Tractability: PROTAC: ubiquitination databases record sites on it; its protein half-life has been measured.
Gene: Protein-coding gene on chromosome 5 (160,009,100 to 160,065,550, forward strand). Ensembl gene ENSG00000113312.
Subcellular location (Human Protein Atlas): Cytosol
Gene Ontology:
Molecular function: protein binding; protein-macromolecule adaptor activity
Biological process: chemokine-mediated signaling pathway; positive regulation of inflammatory response; positive regulation of neuroinflammatory response; protein folding
Cellular component: cytosol; peroxisomal membrane; cytoplasm
Genetic constraint (gnomAD): Loss-of-function variants: 21 observed, 27.43 expected, observed/expected ratio (o/e) 0.77, 90% interval 0.54 to 1.1. The upper end of that interval is the gene's LOEUF score, 1.1, which puts it in group 4 of 6, group 1 being the genes least tolerant of losing a copy. Missense variants: 300 observed, 302.46 expected, observed/expected ratio (o/e) 0.99, 90% interval 0.9 to 1.09. Synonymous variants: 116 observed, 115.75 expected, observed/expected ratio (o/e) 1, 90% interval 0.86 to 1.17.
Homologues: Orthologues: chimpanzee TTC1 (99% identical), macaque TTC1 (93% identical), dog TTC1 (88% identical), guinea pig TTC1 (88% identical), rabbit TTC1 (87% identical), mouse Ttc1 (83% identical), pig TTC1 (76% identical), rat Ttc1 (71% identical), zebrafish ttc1 (56% identical), tropical clawed frog ttc1 (50% identical), Drosophila melanogaster Ttc1 (40% identical). Paralogues in human: SPAG1 (23% identical), RPAP3 (22% identical), TTC4 (20% identical), DNAAF4 (19% identical), SGTA (19% identical), UNC45A (18% identical), UNC45B (18% identical), STIP1 (18% identical), ST13 (18% identical), SGTB (17% identical), SPATA16 (17% identical), STUB1 (17% identical), and 6 more.
Diseases named in the same sentence as TTC1 in open-access papers:
TTC1 is named in the same sentence as 8 diseases in open-access papers, as found by Europe PMC text mining. Sharing a sentence is not in itself a finding about the gene and the disease. The quoted sentences say what the papers report.
anxiety disorder (1 paper, 2013). A category of psychiatric disorders which are characterized by anxious feelings or fear often accompanied by physical symptoms associated with anxiety. "The aim of the current paper is to study the associations of CRY1, CRY2 and TTC1 genes in depressive and anxiety disorders." (PMID 23951166, 2013). "Our objective was to study two core circadian clock genes, CRY1 and CRY2 as well as TTC1 that interacts with CRY2, in relation to depressive and anxiety disorders." (PMID 23951166, 2013).
liver cancer (1 paper, 2025). An epithelial or non-epithelial malignant neoplasm that arises from the liver. "Further bioinformatic analysis indicated that TTC1 may act as a downstream effector of p62, an oncogenic scaffold protein involved in the dysregulation of multiple liver cancer-related genes." (PMID 41268553, 2025).
tumor (2 papers, 2016 to 2025). "TTC1, which has been implicated in cell cycle regulation and apoptosis, was significantly overexpressed in tumor tissues relative to adjacent normal tissues, suggesting that it plays a vital role in HCC pathogenesis." (PMID 41268553, 2025). "Consistent with the database predictions, TTC1 and G6PD mRNA levels were markedly higher in tumor tissues than in matched normal tissues, which mirrors their elevated protein levels in tumors." (PMID 41268553, 2025). "The average expression levels of VPS45, WIPI1, TTC1, IGBP1 and KLHL21 genes in all tested HCC tissues were greatly increased compared with those in the adjacent non-tumor tissues, showing the similar results to microarray data." (PMID 27769251, 2016). "We also validated TTC1, PANK2 and G6PD expression levels in tumor by RT-qPCR." (PMID 41268553, 2025). "Notably, TTC1 and G6PD exhibited significantly higher expression levels in tumor cells comparedto other cell types within the TME." (PMID 41268553, 2025).
TTC1 also shares sentences with these, for which no sentence is quoted: infection (4 papers); Autoimmunity (1); intracerebral hemorrhage (1); major depressive disorder (1); Parkinson disease (1).